KCNE1 (potassium voltage-gated channel subfamily E regulatory subunit 1)
Description:
Ancillary protein that functions as a regulatory subunit of the voltage-gated potassium (Kv) channel complex composed of pore-forming and potassium-conducting alpha subunits and of regulatory beta subunits. KCNE1 beta subunit modulates the gating kinetics and enhances stability of the channel complex. Associates with KCNQ1/KVLQT1 alpha subunit to form the slowly activating delayed rectifier cardiac potassium (IKs) channel responsible for ventricular muscle action potential repolarization. The outward current reaches its steady state only after 50 seconds (Probable). Assembly with KCNH2/HERG alpha subunit Kv channel may regulate the rapidly activating component of the delayed rectifying potassium current (IKr) in heart.
Synonyms: MinK; IsK; JLNS2; LQT5; JLNS; LQT2/5
Tractability: Small molecule: a high-quality ligand is known; it has a binding pocket of medium quality; it belongs to a druggable protein family. Antibody: UniProt places it where antibodies can reach, with high confidence; its Gene Ontology location is reachable by antibodies, with high confidence; UniProt predicts a signal peptide or a membrane-spanning region. PROTAC: a small molecule that binds it is known.
Target class: Slow voltage-gated potassium channel accessory protein family; Auxiliary transport protein
Safety:
Unwanted effects reported when the protein is acted on. In parentheses: how it was acted on, where the effect was seen, and who reports it.
atrial fibrillation (activation; cardiovascular system; source: Bowes et al. (2012))
deafness (inhibition; cardiovascular system; source: Bowes et al. (2012))
gastrointestinal symptoms (inhibition; cardiovascular system; source: Bowes et al. (2012))
long QT syndrome (inhibition; cardiovascular system; source: Bowes et al. (2012))
potential hearing impairment (inhibition; cardiovascular system; source: Bowes et al. (2012))
Acquired Long QT Syndrome (source: ClinPGx)
torsades de pointes (source: ClinPGx)
Gene: Protein-coding gene on chromosome 21 (34,446,688 to 34,512,214, reverse strand). Ensembl gene ENSG00000180509.
Subcellular location: Cell membrane; Apical cell membrane; Membrane raft
Pathways (Reactome):
Muscle contraction: Phase 2 - plateau phase; Phase 3 - rapid repolarisation
Gene Ontology:
Molecular function: delayed rectifier potassium channel activity; potassium channel regulator activity; protein binding; telethonin binding; voltage-gated potassium channel activity; voltage-gated potassium channel activity involved in cardiac muscle cell action potential repolarization; voltage-gated potassium channel activity involved in ventricular cardiac muscle cell action potential repolarization; transmembrane transporter binding
Biological process: cardiac muscle cell action potential involved in contraction; cellular response to cAMP; membrane repolarization; membrane repolarization during action potential; membrane repolarization during cardiac muscle cell action potential; membrane repolarization during ventricular cardiac muscle cell action potential; negative regulation of delayed rectifier potassium channel activity; positive regulation of potassium ion transmembrane transport; potassium ion export across plasma membrane; potassium ion transmembrane transport; regulation of heart rate by cardiac conduction; regulation of membrane potential; regulation of potassium ion transmembrane transport; regulation of potassium ion transport; regulation of ventricular cardiac muscle cell membrane repolarization; ventricular cardiac muscle cell action potential; cardiac muscle cell contraction; negative regulation of protein targeting to membrane; sensory perception of sound; monoatomic ion transport; potassium ion transport; secretory granule organization; vestibular nucleus development
Cellular component: cell surface; lysosome; membrane raft; plasma membrane; voltage-gated potassium channel complex; apical plasma membrane; Z disc; membrane
Genetic constraint (gnomAD): Loss-of-function variants: 0 observed, 1.81 expected, observed/expected ratio (o/e) 0, 90% interval 0 to 1.43. That is too few expected variants to judge how well the gene tolerates losing a copy. Missense variants: 6 observed, 11.51 expected, observed/expected ratio (o/e) 0.52, 90% interval 0.28 to 1.03. Synonymous variants: 3 observed, 5.01 expected, observed/expected ratio (o/e) 0.6, 90% interval 0.27 to 1.49.
Gene-disease validity (ClinGen):
ClinGen rates the evidence that KCNE1 causes each of these diseases.
long QT syndrome 5 (autosomal dominant): Limited.
Homologues: Orthologues: chimpanzee KCNE1 (97% identical), pig KCNE1 (78% identical), rat Kcne1 (77% identical), guinea pig KCNE1 (76% identical), mouse Kcne1 (76% identical), rabbit KCNE1 (73% identical), tropical clawed frog kcne1 (40% identical). Paralogues in human: KCNE2 (23% identical).
Diseases named in the same sentence as KCNE1 in open-access papers:
KCNE1 is named in the same sentence as 68 diseases in open-access papers, as found by Europe PMC text mining. Sharing a sentence is not in itself a finding about the gene and the disease. The quoted sentences say what the papers report.
long QT syndrome (30 papers, 2009 to 2025). "Loss-of-function mutations in KCNQ1 and KCNE1 cause long QT syndrome (LQTS) types 1 and 5 (LQT1/LQT5), accounting for over one-third of clinical LQTS cases." (PMID 41034624, 2025). "Mutations in the KCNE1 gene are the most common cause of congenital defects in long QT syndrome, a heart condition." (PMID 38306576, 2024). "Glycosylation site mutations in potassium voltage-gated channel subfamily E member 1 (KCNE1) give rise to a form of the Long-QT syndrome, a heart rhythm disorder." (PMID 33830329, 2021). "Mutations in the KCNQ1 and KCNE1 interface cause long QT syndrome and atrial fibrillation which results in prolongation of the QT interval of heart repolarization." (PMID 31941450, 2020). "Mutations in cardiac KCNQ1/KCNE1 channels are the most common cause of congenital defects that cause long QT syndrome (LQTS)." (PMID 33322401, 2020). "The acute effect of MeHg on hKv4.3; hERG and hKCNQ1/KCNE1 currents and their transposition to in silico models show an association between MeHg intoxication and acquired Long QT Syndrome in humans." (PMID 32429059, 2020). "Hundreds of mutations in the genes (KCNQ1 and KCNE1) encoding the IKs channel cause long QT syndrome (LQTS)." (PMID 33322401, 2020). "As many cardiac ion channel subunits are glycosylated, hereditary mutations in the glycosylation motifs of hERG and KCNE1 channels have been reported to be causative of long-QT syndrome." (PMID 31635148, 2019). "Lopes and colleagues found that the long QT syndrome-associated mutation R366Q increased the sensitivity of KCNQ1+KCNE1 channels to PIP2 hydrolysis." (PMID 24904429, 2014). "The gene family KCNE1-5, which encode modulating β-subunits of several repolarising K+-ion channels, has been associated with genetic cardiac diseases such as long QT syndrome, atrial fibrillation and Brugada syndrome." (PMID 21967835, 2011). "Variants of KCNE1 have repeatedly been linked to the long-QT syndrome (LQTS), a disorder which predisposes to deafness, ventricular tachyarrhythmia, syncope, and sudden cardiac death." (PMID 19660109, 2009). "Notably, Kcne1, a gene associated with long QT syndrome which is involved in the regulation of cardiac repolarization, was significantly upregulated in BubR1 hypomorphic hearts." (PMID 40607964, 2025). "KCNE1 variants are associated with long QT syndrome and atrial fibrillation." (PMID 38816749, 2024). "Case 1 had Asp85Asn-KCNE1, AD inheritance of a long QT syndrome (LQTS)-related gene variant." (PMID 34728707, 2021). "Furthermore, in patient 32 we discovered a variant (c.253G > A, p.Asp85Asn, and rs1805128) in the KCNE1 gene that has been reported to be associated with long QT syndrome." (PMID 32695137, 2020). "Mutations in either KCNQ1 or KCNE1, with a subsequent reduction of the current, may lead to congenital long QT syndrome." (PMID 29259974, 2017). "Finally, the functional KCNE1 Asp85Asn polymorphism (rs1805128), which occurs in the general population with a frequency of 0.8 %, occurs at a frequency of 3.9 % in long QT syndrome patients." (PMID 23820649, 2013). "Furthermore, IKs is very sensitive to mutations in the KCNE1 C-terminus and several of these mutations have been linked to the long QT syndrome." (PMID 22073228, 2011). "KCNE1 (minK) as a membrane-spanning protein modulates potassium channel functions in cardiac cellular electrophysiology, and its 112G > A polymorphism increases the risk of atrial fibrillation and is also associated with the long-QT syndrome and cardiac arrest." (PMID 35178459, 2022). "Hence, an activated CaMKII in diabetic patients may cause a pathological CaMKII interaction with Kv7.1 or KCNE1, leading to a subsequent long QT syndrome and cardiac dysfunction." (PMID 29259974, 2017).
long QT syndrome (continued). "Susceptibility genes can be analyzed, such as KCNQ1, KCNH2, KCNE1, and KCNE2, which are involved in long QT syndrome, the RYR2 gene implicated in catecholaminergic polymorphic ventricular tachycardia type 1, or the SCN5A gene associated with Brugada syndrome." (PMID 40361926, 2025). "There are few reports of deletions in KCNE1 and those have been identified in patients with long QT syndrome." (PMID 37498360, 2023). "We observed variants at loci containing genes previously established to cause monogenic long-QT syndrome and encoding ion channels or channel-interacting proteins (KCNQ1, KCNH2, SCN5A-SCN10A, and KCNE1)." (PMID 32527199, 2020). "They studied the long QT syndrome-associated mutations R539W and R555C, located within helix C of the C-terminus, and found that these mutations decrease the apparent affinity KCNQ1+KCNE1 channels to exogenous PIP2." (PMID 24904429, 2014). "In this context, susceptibility genes can be analyzed, such as KCNQ1, KCNH2, KCNE1, and KCNE2, which are involved in long QT syndrome, the RYR2 gene implicated in catecholaminergic polymorphic ventricular tachycardia type 1, or the SCN5A gene associated with Brugada syndrome." (PMID 40361926, 2025). "Long QT syndrome is caused by mutations in genes encoding cardiac ion channels (such as KVLQT1, HERG, KCNE1, and KCNE2) leading to prolonged cardiac action potential by either increasing depolarization or decreasing repolarization current and so causing syncope, seizures or sudden death." (PMID 23095120, 2012). "In the context of therapy of the long QT syndrome, activation of KCNQ1/KCNE1 channels was discussed as a therapy option." (PMID 32338831, 2020). "Because KV7.1 is co-assembled with KCNE1 in the native IKs channel complex in the heart, KV7.1 channel activators must affect the KV7.1+KCNE1 complex (referred to as KV7.1+E1) to prevent cardiac arrhythmias, such as in Long QT syndrome." (PMID 30014849, 2018).
atrial fibrillation (21 papers, 2006 to 2025). A disorder characterized by an electrocardiographic finding of a supraventricular arrhythmia characterized by the replacement of consistent P waves by rapid oscillations or fibrillatory waves that vary in size, shape and timing and are accompanied by an irregular ventricular response. "Experimentally, a deletion in KCNE1 has been found to increase susceptibility to atrial fibrillation in mice." (PMID 37498360, 2023). "Our findings show that in the presence of KCNE1, the two atrial fibrillation mutations slow current deactivation by altering the gating pathway of deactivation." (PMID 28383569, 2017). "Recently, many studies have investigated the relationship between human atrial fibrillation and the single nucleotide polymorphism (SNP) of rs1805127 (A>G) in KCNE1 gene, but the results were still inconsistent and inconclusive." (PMID 23874724, 2013). "Lai reported that the variant G allele was more common in AF patients compared with that of control subjects, the result showed that KCNE1 polymorphism was associated with atrial fibrillation." (PMID 23874724, 2013). "The atrial fibrillation-associated KCNE1-38G allele results in reduced IKs density possibly due to impaired membrane trafficking of IKs channels." (PMID 22073228, 2011). "A population study described an association of the common allele KCNE1-38G with atrial fibrillation, a highly prevalent human arrhythmia." (PMID 22073228, 2011). "In clinical studies, the KCNE1 single nucleotide polymorphism G38S has been associated with atrial fibrillation." (PMID 22073228, 2011). "While most evidence suggests a role of KCNE1 transmembrane domain and C-terminus for the interaction, the N-terminal KCNE1 polymorphism 38G is associated with reduced IKs and atrial fibrillation (a human arrhythmia)." (PMID 22073228, 2011). "We have performed a detailed electrophysiological and biochemical analysis of structural determinants underlying reduced IKs with the atrial fibrillation-related single nucleotide polymorphism KCNE1-38G." (PMID 22073228, 2011). "The role of the S1 C-terminus in proper KCNE1 function and its importance in channel gating is underscored by the recently described familial atrial fibrillation mutation in S140G." (PMID 18398469, 2008). "Mutations in potassium channels, KCNJ2 and KCNE1-5, rarely cause typical atrial fibrillation in a referral clinic population." (PMID 16887036, 2006). "Mutations in KCNJ2 and KCNE1-5 rarely cause typical atrial fibrillation in a referral clinic population." (PMID 16887036, 2006). "Finally, as reported in population studies, KCNE1-p.G38S is associated with heart failure, atrial fibrillation, abnormal cardiac repolarization, and an increased risk of ventricular arrhythmia." (PMID 28749435, 2017). "It was also found that the protein KCNE1 gene encoded may work through interacting with other proteins, forming arrhythmogenic substrate and resulting in atrial fibrillation and maintaining." (PMID 23874724, 2013). "We sought to determine if mutations in KCNJ2 and KCNE1-5 are a common cause of atrial fibrillation." (PMID 16887036, 2006). "Gain-of-function mutations in either KCNQ1 or KCNE1 genes shorten the action potential duration and effective refractory period in cardiomyocytes, increasing the risk of atrial fibrillation (AF)." (PMID 32164657, 2020). "Previous modelling studies of IKs with KCNE1 polymorphism alleles showed the generation of early after-depolarisations with the atrial fibrillation-associated ‘38G’ under specific conditions that might cause enhanced automaticity and thus trigger the arrhythmia." (PMID 22073228, 2011). "Two patients with atrial fibrillation due to gain-of-function mutations in KCNQ1 (R670K) and KCNE1 (G60D) were BMI-, age-, and sex-matched to six control participants and underwent a 6-h oral glucose tolerance test (OGTT)." (PMID 32164657, 2020).
atrial fibrillation (continued). "Some of the identified variants have previously been associated with arrhythmia, i.e. p.S38G in KCNE1 and p.P33S in KCNE5, that are known polymorphisms associated with increased risk of atrial fibrillation." (PMID 21967835, 2011). "Western-blots from plasma-membrane preparations and confocal images consistently showed a greater amount of Kv7.1 protein at the plasma-membrane in cells co-transfected with the non-atrial fibrillation KCNE1-38S than with any other construct." (PMID 22073228, 2011). "Conversely, a neighboring mutation that also causes atrial fibrillation, V141M, has minimal effect on current and voltage sensor movement in the absence of KCNE1." (PMID 28383569, 2017). "The KCNE1-c.G112A (p.G38S) variant has been reported to reduce KCNH2 and KCNQ1 channel currents, enhance KCNH2 susceptibility to QT-prolonging factors, and increase the risk for LQTS, atrial fibrillation, and heart failure." (PMID 28749435, 2017). "We first used a single pulse protocol to determine whether the atrial fibrillation mutations S140G and V141M affect channel current and voltage sensor movement in the absence of KCNE1." (PMID 28383569, 2017).
Arrhythmia (19 papers, 2011 to 2026). Any cardiac rhythm other than the normal sinus rhythm. "Our group has previously shown that carriers of pathogenic/likely pathogenic KCNE1 variants in the electronic MEdical Records and GEnomics (eMERGE) sequencing study had longer QT intervals and higher odds of arrhythmia diagnoses and phenotypes." (PMID 38816749, 2024). "Loss of soluble Klotho promotes cardiac arrhythmia owing to decreased activity of the KCNQ1/KCNE1 channels in cardiomyocytes." (PMID 35406743, 2022). "Decrease in KCNQ1/KCNE1 current is known to be associated with prolongation of action potential and cardiac arrhythmias." (PMID 34907346, 2021). "Mutations in both the KCNQ1 and the KCNE1 subunits that decrease channel function are linked to Long QT syndrome, a disease that causes increased susceptibility to cardiac arrhythmias and sudden death." (PMID 32833978, 2020). "More than 300 mutations in the genes encoding for KV7.1 and KCNE1 have been found in patients with cardiac arrhythmias." (PMID 30014849, 2018). "However, mutations in the Kv7.1/KCNE1 channel, which generates the IKs, can cause fatal cardiac arrhythmia." (PMID 37569465, 2023). "On the basis of the data collected in this study, we may speculate that the presence of KCNH2-p.C108Y, together with three KCNE1-p.G38S alleles, could lead to an increased risk of developing cardiac arrhythmias due to the prolongation of the QT interval." (PMID 28749435, 2017). "Klotho counteracts cardiac arrhythmia by ensuring the cell surface expression of KCNQ1/KCNE1 K+ channels that are involved in cardiac repolarization." (PMID 35406743, 2022). "PUFA analogues that are more selective for Kv7.1/KCNE1 are able to restore a prolonged ventricular action potential and prevent arrhythmia in simulated cardiomyocytes." (PMID 32207683, 2020). "One study suggested that the repolarization reserve of KCNQ1/KCNE1 channels is important to prevent the development of ischemia- and reperfusion-induced arrhythmias." (PMID 33322401, 2020). "Dysfunctional KCNQ1/KCNE1 channels prolong the APD and cause life-threatening LQTS and cardiac arrhythmias." (PMID 33322401, 2020). "We validated and optimized the NGS platform with a subset of 46 patients by comparison with Sanger sequencing of coding exons of major arrhythmia risk-genes (KCNQ1, KCNH2, SCN5A, KCNE1, KCNE2, RYR2)." (PMID 31337358, 2019). "Consequently, PBA derivatives more selective for cardiac KCNQ1/KCNE1 channels can be potent activators for treatment of cardiac arrhythmias." (PMID 33322401, 2020). "Modulation of KCNQ1 and KCNE1 might be the mechanism of puerarin in the clinic treatment of arrhythmia." (PMID 27762288, 2016). "Since neurohormones modulated ion channel function and expression, which led to arrhythmia, the transcript levels of Scn5A, KChIP2 and Kcne1 were detected by qPCR, and the results showed that acupuncture tended to increase Scn5A and KChIP2 but decrease Kcne1 expression levels." (PMID 35484628, 2022). "In addition to simulating the effects of PUFA analogues on the ventricular action potential duration, we also simulated the ability of 7 μM DHA-glycine (the most selective Kv7.1/KCNE1 activator) to prevent arrhythmia by simulating early afterdepolarizations using 0.1 μM dofetilide." (PMID 32207683, 2020). "Recently, PUFAs have drawn more and more attention as they have been demonstrated to activate KCNQ1/KCNE1 channels efficiently, making PUFAs a promising approach for treating LQTS and cardiac arrhythmias." (PMID 33322401, 2020). "Therefore, a reduction in KCNQ1/KCNE1 might play a similar role in developing arrhythmia in both congenital LQTS and ischemia- and reperfusion-induced arrhythmias." (PMID 33322401, 2020).